CD4 (CD4 molecule)
Diseases named in the same sentence as CD4 in open-access papers (continued):
Sharing a sentence is not in itself a finding about the gene and the disease.
Hypertension (continued). "A Ugandan study reported increased risk of hypertension after initiation of ART among adults with low nadir CD4 counts, and a US-based study found longer ART use was associated with higher incidence of hypertension." (PMID 30735518, 2019). "In our systematic review, we found that an improved immune status as determined by higher CD4 T cells was associated with higher hypertension prevalence." (PMID 31165257, 2019). "Ang II–dependent hypertension was associated with an increased percentage of both IL17+CD4+ T cells and IL17+CD3+CD4−CD8− T cells in perivascular adipose tissue." (PMID 31321561, 2019). "In a cohort of clinically stable HIV infected patients the prevalence of interatrial blocks, specially advanced, is high and associated to previously known factors (age, hypertension) and novel ones (nadir CD4 lymphocyte count)." (PMID 31622385, 2019). "HIV infection and immunosuppression (CD4 ≤200 cells/mm3) were associated with significantly lower baseline rates of hypertension, when adjusted for other contributing factors." (PMID 30735518, 2019). "There was a statistically significant association between BMI as a categorical variable and both hypertension (Fisher's exact, p = 0.010) and CD4 cell count (Fisher's exact, p = 0.012)." (PMID 29610680, 2018). "Adjusting for BMI reduced the strength of the association between hypertension and CD4 cell count, indicating a positive confounding effect from BMI." (PMID 29610680, 2018). "As such, any attempt to fully elucidate the direct link between hypertension and CD4 cell count should therefore take into consideration the effect of all these important factors associated with hypertension." (PMID 29610680, 2018). "There was a reduction in the strength of association between CD4 cell count and hypertension after adjusting for BMI, suggestive of a positive confounding effect by BMI (Mantel Haenszel pooled odds ratio: 2.50) (95% CI: 1.05–5.93, p = 0.032)." (PMID 29610680, 2018). "Raised BMI, which is associated with hypertension, was found to also have an association with higher CD4 cell counts, making it a potential confounder of the association between hypertension and CD4 cell count." (PMID 29610680, 2018). "Focus is given to the most common comorbidities (such as CKD, CVD, type-II diabetes mellitus, dyslipidemia and hypertension), related risk factors but also demographics, treatment and disease markers (i.e. CD4 cell count and HIV-RNA viral load)." (PMID 30208097, 2018). "The aim of this study was therefore to assess if there is an independent relationship between CD4 cell count and hypertension in HIV/AIDS patients and if this association is modified or confounded by the BMI." (PMID 29610680, 2018). "Patientswith poorer health status at ART initiation (i.e. WHO III/IV stage, low CD4 count, low hemoglobin levels and low BMI) had a decrease risk of prevalent hypertension." (PMID 30281618, 2018). "This is confirmed by the fact that we later on found an association between the CD4 cell count as a binary variable and hypertension, with CD4 cell counts of 350 cells/μL and above found to be associated with hypertension." (PMID 29610680, 2018). "A close analysis of the stratum specific odd ratios of the association between hypertension and CD4 cell count across the BMI categories reveals a stronger association among patients with normal BMI compared to overweight patients." (PMID 29610680, 2018). "We found an inverse relationship in patients with a CD4 count <50 cells/mm3 at ART initiation who had a 25% increased risk of incident hypertension compared to those with a CD4 count ≥350 cells/mm3." (PMID 30281618, 2018). "A CD4 cell count ≥ 350 cells/μL was associated with higher odds of hypertension, and the strength of this association decreased after adjusting for BMI." (PMID 29610680, 2018).
Hypertension (continued). "Manner and colleagues showed that nadir of CD4+ T-lymphocytes is an independent risk factor for the development of hypertension in people living with HIV." (PMID 28749986, 2017). "Altogether these findings suggest that activation of CD4+ T cells in hypertension causes interstitial and perivascular fibrosis that leads to functional and morphological changes in the heart conducive to the development of heart failure." (PMID 27795961, 2016). "Augmented infiltration of CD4+ T-lymphocytes is associated with a rapid deterioration of the ejection function in a rat model of spontaneous hypertension." (PMID 26506526, 2015). "Current CD4 T-cell count (OR = 4.33 [1.51 to 12.40] for CD4 T-cell count >500cells/μL versus <200cells/μL) was also significantly associated with hypertension." (PMID 25070128, 2014). "In our study, among HIV-infected adults, the higher CD4+ T-cell counts were associated with more hypertension and higher blood pressures." (PMID 25070128, 2014). "Many of the factors associated with LBW in this study, such as CD4 count and hypertension, have been reported in previous studies." (PMID 21843356, 2011). "Factors associated with SLD were: CD4 T-lymphocyte count > 200 cells/μL (odds ratio [OR]: 3.69; 95% confidence interval [CI]: 1.19–11.44), female sex (OR: 8.5; 95% CI: 2.57–28.17), hypertension (OR: 6.5; 95% CI: 2.05–21.00), and being normal or overweight (OR: 6.75; 95% CI: 1.12–40.56)." (PMID 39822280, 2024). "Th17, a subset of the CD4+ T helper cells, may be involved in the association between irrational dietary pattern and hypertension." (PMID 36678161, 2023). "Interestingly, a higher CD4 count was significantly associated with prevalent hypertension in this study similar to findings from other studies." (PMID 37908015, 2023). "In CD4 memory T cells, in addition to mitochondrial metabolism pathways, we also found pathways related to non-alcoholic fatty liver disease, which has been shown to be associated with the development of hypertension." (PMID 37009484, 2023). "However, recent CD8+ cell counts and CD4+/CD8+ ratio was negatively associated with risk of hypertension." (PMID 37025998, 2023). "However, several studies showed that HIV-related factors such as a low nadir CD4+ T-cell count and longer duration of cART were associated with increased risk of hypertension." (PMID 31929537, 2020). "Particularly, the higher immune activation and systemic inflammation biomarkers levels (sST2 and hsCRP) and the low absolute CD4+ T-cell count could promote an increase of the risk of arterial hypertension and diastolic dysfunction in INRs." (PMID 33071649, 2020). "Interestingly, in our study, recent CD4+/CD8+ ratio among PLWH was associated with incident hypertension [Adjusted HR:0.14 (0.06, 0.31)]." (PMID 32487185, 2020). "Among HIV-infected adult, risk factors for hypertension in univariate analyses included older age, being married, having >1 child, having current employment, having anxiety, more cigarette smoking, more cannabis use, a high BMI, and higher CD4 count." (PMID 30735518, 2019). "Besides traditional risk factors and the effect of ART on blood pressure, IL-17A, IFN-γ, and CD4+ T cells were among the inflammatory parameters associated with hypertension in ART treated PLWH [13••, 56]." (PMID 31165257, 2019). "Nadir CD4 cell count in HIV-infected patients has been shown to be associated with hypertension, through processes of persistent immune activation, chronic inflammation, endothelial dysfunction, and microbial translocation that occurs with inadequate immune recovery." (PMID 29610680, 2018). "The Th17 subset of CD4+ T cells and IL-17 production have been implicated in the pathogenesis of Ang II–induced hypertension and remodeling, and may have reciprocal interactions with Tregs." (PMID 29688896, 2018). "This implies that the association between the CD4 cell count and hypertension could be different across the various BMI categories." (PMID 29610680, 2018).
Hypertension (continued). "This means that the association between hypertension and CD4 cell could exist due to some important confounding." (PMID 29610680, 2018). "These are all in favor of an association between nadir CD4 cell count and hypertension." (PMID 29610680, 2018). "In this study, we aimed to determine if there is an association between blood pressure, hypertension, and CD4 cell count and investigate if this association could vary with changes in BMI." (PMID 29610680, 2018). "Specifically we had as objectives to determine if there is a linear association between blood pressure (BP) values and CD4 cell count and to determine if there is an association between hypertension and CD4 cell count categories after controlling for BMI and other important confounders." (PMID 29610680, 2018). "The association of hypertension with higher CD4 counts and older age suggests that hypertension may be a substantial problem among PLWH in SSA as they age on ART." (PMID 29246206, 2017). "However, the administration of PGG decreased RANTES mRNA level in pVAT during Ang II‐dependent hypertension, which could be associated with decreased T‐cells and infiltration by their subsets (especially CD4+CCR5+ and CD8+CCR5+) into the pVAT." (PMID 30658013, 2019). "It is now becoming apparent that patients with advanced HIV infection and CD4 counts <300 cells/μL may be at risk of developing PRES either in isolation or in the setting of hypertension, hypercalcemia or disseminated opportunistic infection, particularly those penetrating the CNS." (PMID 23981526, 2013). "Among individuals with AHA-defined hypertension, nadir CD4+ T cell counts were significantly lower than those in the non-hypertensive group, and years on ART were significantly longer." (PMID 41216424, 2025). "Although Th17 cells with intracellular IL-17F/IL-22 co-expression constituted <3% of the CD4+ population overall, the more than threefold increase compared to controls suggests their involvement in hypertension in pregnancy." (PMID 41156157, 2025). "PWH with high NT-proBNP were older, predominantly male, had lived with HIV for a longer duration, had a higher prevalence of hypertension and had a lower current CD4 count than those with low NT-proBNP." (PMID 40149937, 2025). "Recent work using the Tg26 mouse model of HIV shows CD4+ T cells expressing viral proteins can drive hypertension through IL-1α and NOX1 pathways." (PMID 41333751, 2025). "Ultimately, infiltration of CD4+ T cells into the paraventricular nucleus marked the establishment of hypertension in these rats." (PMID 40141195, 2025). "The association between the density of CD4+ and CD8+ cells in the tubulointerstitium and treatment response disappeared after further adjusting for gender, age, UPRO, SCr, C4, LN duration, hypertension, repeat biopsy, AIs, CIs, and ISN/RPS classification." (PMID 38415246, 2024). "Kidney injury molecule-1 (KIM-1), a marker of renal tubular injury, was elevated in individuals with both hypertension and hyperuricemia, correlating with increased numbers of CD4+ T cells and macrophages (CD68+)." (PMID 38425055, 2024). "Elevated numbers of CD4+ T cells and macrophages in hypertensive subjects with increased sUA levels suggest a ‘double hit’ model of uric acid amplifying hypertension-induced renal damage and contributing to tubulointerstitial inflammation." (PMID 38425055, 2024). "Since circulating CD8 TEM cells were upregulated in hypertension patients, they demonstrated more biological functions than CD4 TEM cells, along with rapid effector functions." (PMID 37009484, 2023). "High circulating levels of pro-inflammatory CD4+ T cells were found in the patients with hypertension." (PMID 36678161, 2023). "Subsequent studies were conducted to identify the specific subtypes of contributing T cells, resulting in the identification of a variety of T cells that become active within hypertension including γδ, CD4+, and CD8+ T cells." (PMID 36970367, 2023).
Hypertension (continued). "CD4+ T cells, CD8+ T cells, and γδ T cells are closely associated with the development of hypertension." (PMID 36891527, 2023). "The result showed that higher hsCRP, SIRI, NMR, higher recent CD4+ cell counts and recent HIV-RNA of less than 100 Copies/mL were associated with hypertension." (PMID 37025998, 2023). "Multivariable analyses for lipid profile were adjusted for age, gender, body mass index, drinking habit, smoking habit, hypertension, CD4 count, T lymphocyte count and HIV-1 viral load." (PMID 37181701, 2023). "The relationship between dietary factors and subsets of CD4+ T cells was also analyzed to explore the potential mechanism between the whole diet and hypertension." (PMID 36678161, 2023). "PLWH with favourable HIV laboratory parameters at enrollment (WHO clinical stage 1 and 2, Viral load ≤ 1000 copies/ml, and CD4 counts ≥ 201cells/μL) were also found to have higher odds of hypertension." (PMID 37908015, 2023). "In the general population, CD4+ cells are critical to the pathophysiology of hypertension and can produce immunosuppressive cytokines to suppress immune response activation." (PMID 37025998, 2023). "Within hypertension, these γδ T cells as well as CD4+ T cells function by aiding in the activation of CD8+ T cells or through cytokine production, including IFNγ and IL-17A." (PMID 36970367, 2023). "Regarding parameters like TG and HDL-C, abnormal levels were more prevalent in PLWH with hypertension, lower CD4/CD8 ratio, or higher viral load." (PMID 37705002, 2023). "Many studies have shown that the risk factors for hypertension in PLWH include unhealthy lifestyle habits, high body mass index (BMI), hyperlipidemia, adverse effects from ART, CD4+ cell counts, and CD4+/CD8+ ratio." (PMID 37025998, 2023). "In multivariate analysis, factors associated with lower eGFR were female gender (p<0.001), being on treatment for hypertension (p<0.001) and nadir CD4 count < 50 cells/μL (p = 0.008)." (PMID 37352206, 2023). "CD4 T‐cell activity is increased in an angiotensin 2–induced hypertension model, and oxidative injury induces CD4 lymphocyte activation." (PMID 37813528, 2023). "Among our patients, the population of CD4+CD25+Foxp3+ cells was slightly lower in the group of women with hypertension." (PMID 37887878, 2023). "Advanced and severe CD4 counts as well as ART regimens 1T3E and 1TFE were also implicated in causing hypertension in this population." (PMID 36141463, 2022). "Although it has been confirmed that both types of T cells are involved in the initiation and progression of hypertension, results based on in vivo models showed that CD4+ T cells are likely to the key factor in promoting hypertension." (PMID 36703963, 2022). "The proinflammatory profile during ANGII-induced hypertension is accompanied by a destabilized and reduced antiinflammatory CD4+FoxP3+ Treg response along with a decrease in IL-10 production." (PMID 35133978, 2022). "In the Cox multivariate model, patients that had hypertension heredity, BMI ≥ 25 kg/m2, eGFR < 60 mL/min/1.73 m2, advanced and severe CD4 counts, 1TFE and 1T3E regimens, and the male gender were found to be at greater risk of hypertension." (PMID 36141463, 2022). "CMV infection reduces the percentage of CD4+ naïve T cells, which enhances hypertension development, especially in older men." (PMID 35053985, 2022). "Hypertension, together with CD4 recovery, is suggested to be an epiphenomenon of the improvement of the HIV infection state, not the influencing factor." (PMID 36298842, 2022). "Recently, we found that hypertension has the greatest impact on the T cell subpopulation and that it determines the direction of changes in CD4+/CD8+ ratio in the Polish population over 60 years of age." (PMID 35453906, 2022). "Statistically significant differences were observed in the percentage of CD4+ T lymphocytes only in the individuals diagnosed with hypertension when compared to the controls." (PMID 35053985, 2022).
Hypertension (continued). "The present study showed increased CD4+ T lymphocytes in individuals with elevated blood pressure, which emphasizes the role of the immune system in the development of arterial hypertension." (PMID 35053985, 2022). "During inflammation, cardiac fibrosis and hypertension CD4+ CD25+ regulatory T-cells activation proved integral in suppressing inflammatory signals and ameliorating organ damage." (PMID 35955801, 2022). "In particular, IL-17A producing CD4+ TH17 cells are reported to transmit immune reaction in hypertension." (PMID 33561095, 2021). "We found patients receiving second line ART to have higher CD4-cell counts than those receiving first line treatment, especially among those with hypertension." (PMID 34155234, 2021). "In those with decreased baseline CD4 counts, more patients were older (p<0.001), presented as critically ill (p=0.032) and had hypertension (p=0.008) compared with those with normal CD4 counts." (PMID 34149679, 2021). "The transfer of Th17 cells isolated from adult donor SHR blood significantly increases the proportion of CD4+IL-17A+ (Th17) cells in the PBMCs and the spleen of recipient juvenile rats and induces early hypertension in the juvenile recipient SHR." (PMID 33688497, 2021). "After adjusting for age, history of hypertension, shortness of breath, white blood cells, platelets, D-dimer, and CD4/CD8 ratio (Mode 6), the HR for in-hospital death in the group with lower CD4+T cell level was 7.656 (95%CI: 1.610–36.396, P=0.010)." (PMID 33435865, 2021). "Underuse and overuse of medications, advanced HIV stages, adverse effects, line of treatment, age and sex predicted higher viral loads (ART failure) and lower CD4-cell counts in patients with hypertension." (PMID 34155234, 2021). "Accumulating evidence has demonstrated that subsets of CD4+ Th cells are closely related to the development of hypertension and target organ damage." (PMID 32148441, 2020). "Recent low CD4+/CD8+ ratio and detectable HIV viremia were associated with incident hypertension, whereas receipt of ART was associated with reduced risk." (PMID 32487185, 2020). "A similar study conducted in Cambodia using cohort analysis showed an increase in median CD4 counts from 53 to 316 cells/mm3, and that 68% of hypertension patients on regular treatment had their BP controlled after 2 years of implementation of the pilot study." (PMID 32316885, 2020). "Recent low CD4+/CD8+ ratio and detectable HIV viremia were associated with incident hypertension, while receipt of ART was associated with reduced risk." (PMID 32487185, 2020). "In SS rats, it induces hypertension by increasing the population of CD4+IL-17A+ (Th17) cells, which secrete pro-inflammatory cytokine IL-17A." (PMID 32179549, 2020). "Old age, hypertension, higher circulating levels of neutrophils, IL-6, and NLR and lower levels of T lymphocytes, CD4+ lymphocytes, and CD8+ T cells were significantly associated with the risk of developing pneumonia." (PMID 33239109, 2020). "Older age, male gender, BMI > 25 kg/m2, and baseline CD4 cell count ≥ 200 cells/μL were also independent predictors of sustained hypertension." (PMID 31165257, 2019). "In a separate multivariable model, HIV-infected adults with CD4 ≤200 cells/mm3 had a 44% lower odds of hypertension (aOR = 0.56, 95% CI: 0.38–0.83), as compared to adults with CD4 >200 cells/mm3." (PMID 30735518, 2019). "In conclusion, aIAB seem to be more prevalent than expected among PLWH and is related to both previously known (age, sex, hypertension) and novel (nadir CD4) variable." (PMID 31622385, 2019). "PGG also efficiently reduced the content of CD4+ cells bearing CD25 during the development of hypertension." (PMID 30658013, 2019). "In vivo study using an experimental model of Ang II‐dependent hypertension confirmed that PGG also effectively inhibited the production of IL‐17A by CD4+ and CD3+CD4−CD8− T‐cell subsets." (PMID 30658013, 2019).